EGFR (epidermal growth factor receptor)
Diseases named in the same sentence as EGFR in open-access papers (continued):
Sharing a sentence is not in itself a finding about the gene and the disease.
tumor (continued). "We detected tumor-associated transcripts of EGFR and PSMA in patients with metastatic PCa in 42.8% and 14.3% of the analyzed samples, respectively." (PMID 27479125, 2016). "Of the 289 patients who participated in the randomized phase II study, 208 cases with a known EGFR or KRAS mutation status in their tumor tissues were examined." (PMID 27519791, 2016). "In human cancer, sustained EGFR activation is commonly observed due to EGFR overexpression or the mutation of EGFR, leading to various tumor-promoting activities, including the inhibition of apoptosis." (PMID 27888617, 2016). "To test ARPS for this capability, we extracted genomic DNA from known EGFR-mutated tumor cell lines mixed with increasing amounts of wild-type DNA (the total amount of DNA was 300 ng) to assess the sensitivity of our method." (PMID 27223277, 2016). "In November 2015, osimertinib received US Food and Drug Administration (FDA) approval for EGFR–TKI-pretreated metastatic EGFRT790M-positive NSCLC, as did the companion diagnostic test (cobas® EGFR Mutation Test v2) that is used to detect tumor EGFRT790M." (PMID 27912760, 2016). "Twenty-seven samples were analyzed using our tumor genotyping panel, and 34 samples were analyzed for EGFR mutations only by commercial clinical laboratories." (PMID 27821131, 2016). "In our study, we showed that AREG/EGFR co-expression were associated with poor tumor differentiation." (PMID 27391842, 2016). "Positive and negative concordance between ARMS-PCR and SMART methods for detection of 29 hot spot EGFR mutations in tumour specimens was used to judge the performance of both assays." (PMID 27409166, 2016). "Patients should have tumor tissue assessed for the presence of a driver mutation, such as mutated epidermal growth factor receptor (EGFR) or the anaplastic lymphoma kinase (ALK) fusion oncogene." (PMID 28090370, 2016). "Approximately 10% of specimens submitted for EGFR mutation testing were found to contain less than 10% tumor, thereby failing tumor percentage requirements for NGS testing." (PMID 27043212, 2016). "Based on the multivariate analysis, ECOG-PS, tumor stage, histology, EGFR status and NLR were significantly associated with OS." (PMID 27029035, 2016). "Particularly we addressed the impact of respective tumor markers in patients with EGFR mutations as potential prognostic factors." (PMID 27072585, 2016). "At present, molecular characterization of EGFR mutations is performed using DNA extracts from tumour tissue specimens." (PMID 27739449, 2016). "It is worth noting that all patients with mCRC with RAS PLLM and/or RAS mutation in a limited area of the tumor (i.e., intra- or inter-tumoral heterogeneity) treated with anti-EGFR mAbs had disease progression at 2–3 months (n = 5, cases 2, 7, 9, 11 and 12)." (PMID 27916952, 2016). "Tumors with specific genetic alterations, such as KRAS or EGFR mutations, were also distinguished and the location of the primary tumor identified with 71% accuracy." (PMID 28066769, 2016). "Taking the detection of EGFR mutations in tumor tissue as the golden standard, the concordance of the detection of EGFR mutations from ctDNA was 74% (54/73)in our study." (PMID 26989078, 2016). "Another potential cause of the observed discrepancies in EGFR mutation testing between PT and LN specimens is tumor heterogeneity." (PMID 27685950, 2016). "EGFRvIII is a 140-kDa EGFR trans-membrane isoform with a truncated extracellular domain, containing an in-frame deletion of amino acids 6-273, and it is originated by a tumor specific-mutation produced by the deletion of exons 2–7." (PMID 27104520, 2016). "No survival benefit has generally been observed in these studies, attributed to the important crossover to TKI as a second-line treatment in the chemotherapy arms, except for afatinib in patients with a del19 EGFR mutations in the tumor." (PMID 27032107, 2016).
tumor (continued). "Significant associations emerged between EGFR amplification and large tumor size (T4), ER-negative and HER2-positive status, between CCND1 amplification and HER2-positive and MIB1-positive status, and between ESR1 deletion and ER-negative status." (PMID 27765917, 2016). "NGS also identified EGFR mutations in plasma samples from two patients with EGFR wild type tumor tissue." (PMID 27448974, 2016). "To examine the role of the ERBB3-regulating miR-200c target genes in tumour growth, we generated EGFR-mutated H1975 cell transfectants that stably express short hairpin RNAs against TOB1." (PMID 27456471, 2016). "In this study, overall, the tumor cell proportion was not different between PT and LN specimens; however, the three cases that showed discrepancies in major EGFR mutations between paired samples had a low proportion of tumor cells (5–10%) in the LN specimens." (PMID 27685950, 2016). "A significant association between AREG/EGFR co-expression and tumor differentiation was observed in our study (P = 0.032)." (PMID 27391842, 2016). "There were 20 different SNV/InDels (insertions/deletions) identified in the tumor tissue samples from the 12 patient pairs with an EGFR 19 del or L858R mutation (P < 0.05)." (PMID 27001083, 2016). "Patients with an EGFR mutation in their tumor were then treated with erlotinib (150mg/day) until progression." (PMID 26689995, 2016). "In this prospective phase II study in phenotypically selected patients with a somatic EGFR mutation in their tumor erlotinib was well tolerated and highly effective in the majority of the patients." (PMID 27032107, 2016). "KRAS, NRAS and BRAF mutations were detected in two or all three tumor types while mutations in EGFR were uniquely detected in NSCLC." (PMID 27101000, 2016). "EGFR promotes tumor growth and cell motility and has been associated with a poor clinical GB outcome and unfavorable GB presentation." (PMID 25821789, 2015). "Combined BRAF and EGFR inhibition caused a strong synergistic effect in vitro and in xenograft models and resulted in complete inhibition of tumor growth [26••]." (PMID 26617477, 2015). "In some tumor types PIK3CA mutations are frequently associated with EGFR or KRAS mutations and with a poorer prognosis." (PMID 26209091, 2015). "The group of Dr. Rosell in Spain has developed and validated a method for EGFR mutation testing in samples containing less than 150 tumor cells that can be applied to both fresh and paraffin-embedded biopsies and cytologic specimens." (PMID 26022577, 2015). "Although EGFR blockage can enhance apoptosis susceptibility in tumor cells, our data demonstrate that blocking EGFR tyrosine kinase by erlotinib fails to recover ASPP2 overexpression-induced apoptosis in HCC." (PMID 25980493, 2015). "In conclusion, the enhancement of apoptosis caused by treatment with the combination of gefitinib and GA was effective in the suppression of gefitinib-resistant tumor growth caused by a EGFR T790M secondary mutation." (PMID 26622796, 2015). "Mutation analysis of the EGFR gene TK domain exons 18–21 was carried out on tumour specimens drawn from 33 patients of the study." (PMID 25918681, 2015). "Despite the morphologic similarity based on H&E staining, immunoblot analysis of tumor lysates demonstrated that loss of EREG was associated with decreased phosphorylation of EGFR." (PMID 26215578, 2015). "Tumours harbouring KRAS or EGFR mutations had always acquired these in the founding clone, whereas putative driver mutations in HGF were subclonal." (PMID 25555261, 2015). "One sarcomatoid tumor sample harbored four mutations in the EGFR, MEK1, NRAS, and PTEN genes, respectively." (PMID 25470237, 2015). "All CTCs in baseline blood samples from eight NSCLC patients were found to harbor the EGFR mutations that corresponded with tumor tissues." (PMID 26227959, 2015).
tumor (continued). "Of the remaining 17 patients, 15 had detectable activating EGFR mutation in the tumor, whereas 10 patients exhibited this in the plasma cfDNA." (PMID 26334838, 2015). "EGFR amplification was detected in 18 tumor samples (8.9 %) and was significantly associated with higher EGFR protein levels compared to TNBC specimens with normal or deleted EGFR or chromosome 7 polysomy (p = 0.043)." (PMID 26680641, 2015). "In the present study, we evaluated this approach for EGFR mutation detection in tumor tissue gathered during resection and showed the feasibility of using this approach in a cytology sample collected by bronchoscopic examination." (PMID 25591975, 2015). "To address the origin of EGFR activation in Smarcb1 deficient tumor cells we considered various mechanisms that can cause aberrant activation of EGFR and downstream signaling." (PMID 26370283, 2015). "We then sought direct evidence that the decreased tumor cell growth associated with RHBDD1 inactivation was due to decreased TGFα/EGFR signalling." (PMID 26300397, 2015). "Cell lines bearing these mutations revealed increased HER2, EGFR, and PLCγ phosphorylation and had more rapid tumor growth in xenograft models compared to the wild type control." (PMID 25809292, 2015). "Tumours harbouring these EGFR mutations are more sensitive to tyrosine kinase inhibitors (TKI) that target EGFR, such as gefitinib, erlotinib or cetuximab." (PMID 25969993, 2015). "There is no statistical difference in patients with a higher (≥12%) or lower (<12%) increase of anti-ENO1 Ab after surgery with regards to gender, histological subtypes, pTNM stages, tumor volumes, or EGFR mutation status." (PMID 26551021, 2015). "In ccRCC, EGFR overexpression has been shown to be associated with rapid tumor growth and a high tumor grade." (PMID 26426994, 2015). "Following dramatic initial tumor shrinkage,tumor regrowth is most frequently associated with the emergence of a secondary geneticchange, the T790M ‘gatekeeper’ mutation within the EGFR kinase domain,which restores ATP binding in the presence of drug." (PMID 25686219, 2015). "Initially the network construction was based on proteins exclusively expressed in tumours and by selecting master regulatory proteins linked to EGFR signalling." (PMID 25872475, 2015). "Compelling evidence has underlined the importance of the EGFR and NF-κB pathways in the regulation of tumor cell migration and invasion, the latter by regulating the expression of matrix metalloproteinases." (PMID 26480820, 2015). "In each case, the same EGFR mutation was detected in both components of the tumor indicating a monoclonal origin of ADSQ." (PMID 26068980, 2015). "EGFR is frequently overexpressed and mutated in various types of tumor, including lung cancer, oral squamous cell carcinoma and breast cancer." (PMID 25997612, 2015). "Afatinib has anti-tumor effect in NSCLC with activating EGFR mutations, approved by EU, US FDA and Taiwan FDA." (PMID 25537503, 2015). "Within the nucleus, EGFR can function as a cotranscription factor to regulate genes involved in tumor progression, which has been linked to anti-EGFR therapies resistance." (PMID 26258011, 2015). "Out of 2,450 diagnostic samples (containing >10 % of tumor cells), the occurrence of EGFR gene mutations was 9 %; more frequently in women (13.9 %) and adenocarcinoma patients (10 %), particularly with accompanying expression of TTF1 (13.0 %)." (PMID 25086987, 2015). "National comprehensive cancer network (NCCN) guidelines state that DNA mutational analysis in tumor cells is the preferred method to assess EGFR gene mutation status." (PMID 26047516, 2015). "With the aim of obtaining a patient’s genomic profile from CTCs, we performed Sanger direct sequencing to detect a number of mutations in the EGFR of single tumor cells which had been isolated from the microwell array." (PMID 26107884, 2015).
tumor (continued). "In this study, we identified a novel small molecule inhibitor, WB-308, which targets the kinase activity of EGFR and EGFR-mediated tumor growth-associated gene expression." (PMID 25730907, 2015). "Here, we investigated EGFR domain III and activating RAS mutations in a “tumor tissue” cohort of 21 patients with gastrointestinal cancers, mainly mCRC, including 16 patients with EGFR-targeted therapy." (PMID 26059438, 2015). "We compared the abilities of enrichment PCR followed by ultra-deep pyrosequencing (UDP), UDP alone, and PNA-mediated RT-PCR clamping to detect low-frequency EGFR mutations in tumor cell lines and tissue samples." (PMID 25915533, 2015). "As far as we are aware, no previous study has demonstrated a significant correlation of T790M mutation between tumor samples and plasma cfDNA in individuals with EGFR-mutant NSCLC that has acquired resistance to EGFR-TKIs." (PMID 26334838, 2015). "In the case of neoplasia however, the EGFR is often chronically stimulated, either by EGFR ligands that are over-produced within the tumor microenvironment or as a result of EGFR mutation that causes spontaneous receptor activation." (PMID 25629807, 2015). "The assessment of EGFR gene mutation status in tumor tissue has important predictive value and can be used to select therapies for the treatment of NSCLC." (PMID 26047516, 2015). "It has become a well-established fact that overexpression of EGFR in tumor is common in many types of cancer and is associated with poor outcomes of them." (PMID 26474280, 2015). "Afatinib has showed the preclinical activity in tumor models with EGFR-TKI resistant mutation T790M." (PMID 25714021, 2015). "Resistance to first-line tyrosine kinase inhibitors (TKIs) in NSCLC is often driven by the development of tumor clones harboring EGFR T790M mutations." (PMID 26474073, 2015). "The effects of EGFR over-expression and mutation on proliferation, migration, invasion, response to gefitinib, and tumour formation in vivo was investigated." (PMID 25969993, 2015). "Next, we compared the mutational spectrum of pre-treatment primary tumours and two EGFR-TKI-refractory liver metastases, one with adenocarcinoma and the other with SCLC." (PMID 26400668, 2015). "Overexpression or mutation of EGFR is often responsible for tumor resistance to both chemotherapy and radiotherapy." (PMID 26480820, 2015). "The FDA recommends that CRC patient tumor biopsies be assessed for KRAS mutation status prior to treatment with anti-EGFR mAbs." (PMID 25823645, 2015). "It is notable that the EGFR mutation status (exons 18, 19, 20 and 21) from two tumor samples were examined by sequencing method, including a young female who had never smoked, but no mutations were detected." (PMID 25663934, 2015). "Epidermal growth factor receptor mutations with the exon 19 deletion have been proposed to reduce the growth capacity of tumor cells, leading to smaller-sized BMs." (PMID 26014133, 2015). "As EGFR TKIs, erlotinib and Gef show similar anti-tumour activity in NSCLC patients harbouring EGFR mutation." (PMID 26635117, 2015). "One of the commonly found tumor-cell subpopulations in GBM has an abnormality in EGFR (overexpression, gene amplification, and/or mutation)." (PMID 26307682, 2015). "In many cases, even though these samples contain a very small amount of tumor cells, our method can detect the major EGFR mutations." (PMID 25651992, 2015). "Of note, both models have some degree of genetic similarity with the tumor profile of the patient described in this report (likely positive for EGFRvIII mutation and positive for EGFR amplification)." (PMID 26423602, 2015). "EGFR inhibitors target aberrantly activated or overexpressed EGFR in tumor cells, causing cellular apoptosis by inhibiting metastasis, growth, proliferation, differentiation and angiogenesis." (PMID 26361513, 2015).
tumor (continued). "In the current study, gefitinib in combination with GA resulted in antitumor growth in the EGFR-T790M secondary mutation NCI-H1975 tumor model due to an enhanced apoptotic effect." (PMID 26622796, 2015). "miR-7 was implicated in GBM as a tumor suppressor by regulating epidermal growth factor receptor (EGFR) and the Akt pathway." (PMID 26064134, 2015). "EGFR mutations were found in 191 (9.2 %) cases out of 2,079 samples with ≥20 % tumor cells and in 30 (8.1 %) cases out of 371 samples of <20 % tumor cells." (PMID 25086987, 2015). "About 50%–60% of patients with EGFR mutation-positive tumours progressing after first-line treatment on an EGFR TKI become resistant via the acquisition of the secondary gatekeeper mutation T790M." (PMID 26410619, 2015). "The comparative in vivo evaluation of [11C]erlotinib with the irreversible inhibitor [18F]afatinib has been recently described in mutation sensitized and wild-type EGFR-expressing tumor bearing mice." (PMID 26690113, 2015). "We present our experience on the efficacy of routine EGFR testing in various types of tumor samples and the frequency of EGFR mutations in a large series of Polish non-small cell lung cancer (NSCLC) patients." (PMID 25086987, 2015). "The close association between mPGES-1 and EGFR expression observed in these tumours led us to detailed study of this connection in experiments on hormone-independent PCa cells DU145 and PC-3 in vitro and in vivo." (PMID 26113609, 2015). "Each of high EGFR and low Beclin1 protein expression, independently, has been associated with tumor progression and poor prognosis." (PMID 25821789, 2015). "Further studies are required to clarify the biological features of these tumours and to investigate the mechanisms underlying the primary resistance to EGFR-TKIs when the EML4-ALK rearrangement is present." (PMID 25788996, 2015). "Unusually, two patients with an EGFR mutation (one with the mutation in their primary tumour and one with the mutation in a lymph node metastasis) had an additional KRAS mutation in the corresponding metastases." (PMID 26338018, 2015). "Cytological and small biopsy samples with low (10–20 %) content of tumor cells and specimens from metastatic lesions are a sufficient source for EGFR mutation testing in NSCLC patients." (PMID 25086987, 2015). "The existence of EGFR and other mutations within the same tumor sample identified by NGS highlights the importance of this type of analysis in guiding appropriate cancer therapy." (PMID 26572169, 2015). "Isolation of single captured tumor cells, followed by detection of EGFR mutations, was achieved using Sanger sequencing." (PMID 26107884, 2015). "In a following proof-of-concept study, the correlative relationship between EGFR mutation status, in this case the 19 exon deletions, and [11C]erlotinib tumor uptake was demonstrated." (PMID 26690113, 2015). "To date, the selection of candidate patients for first-line treatment with EGFR TKIs requires an invasive tumor biopsy to affirm the mutational status of the receptor." (PMID 25853010, 2015). "Many researches have reported that these mutations are tumorigenic in vivo and that these mutations sensitize the tumor to EGFR TKI treatment." (PMID 26375550, 2015). "Similar to COX-2, EGFR is overexpressed in many human tumor types and is associated with poor prognosis and decreased survival." (PMID 25595899, 2015). "More specifically, they can be classified into lncRNA signature subgroups: (i) astrocytic tumor with high EGFR amplification; (ii) neuronal-type tumor; and (iii) oligodendrocytic tumor enriched with IDH1 mutation and 1p19q co-deletion." (PMID 26230711, 2015). "Several studies have demonstrated that EGFR mutation status in CTCs matches well with that in tumor tissues." (PMID 26227959, 2015). "For example, in non-small cell lung cancer (NSCLC), a gefitinib resistance-conferring mutation in EGFR (T790M) has been identified in the pre-treatment tumor or circulating tumor cells." (PMID 26105199, 2015).